MAGI3 (membrane associated guanylate kinase, WW and PDZ domain containing 3)
Description:
Acts as a scaffolding protein at cell-cell junctions, thereby regulating various cellular and signaling processes. Cooperates with PTEN to modulate the kinase activity of AKT1. Its interaction with PTPRB and tyrosine phosphorylated proteins suggests that it may link receptor tyrosine phosphatase with its substrates at the plasma membrane. In polarized epithelial cells, involved in efficient trafficking of TGFA to the cell surface. Regulates the ability of LPAR2 to activate ERK and RhoA pathways. Regulates the JNK signaling cascade via its interaction with FZD4 and VANGL2.
Synonyms: MAGI-3; dJ730K3.2
Tractability: Antibody: UniProt places it where antibodies can reach, with medium confidence; its Gene Ontology location is reachable by antibodies, with medium confidence. PROTAC: UniProt records ubiquitination sites on it; ubiquitination databases record sites on it; its protein half-life has been measured; a small molecule that binds it is known.
Target class: Enzyme
Gene: Protein-coding gene on chromosome 1 (113,390,501 to 113,685,923, forward strand). Ensembl gene ENSG00000081026.
Subcellular location: Cell membrane; Cell junction, tight junction; Nucleus
Subcellular location (Human Protein Atlas): Cell Junctions
Gene Ontology:
Molecular function: enzyme-substrate adaptor activity; protein binding; GMP kinase activity; frizzled binding
Biological process: apoptotic process; intracellular signal transduction; signal transduction; GDP metabolic process; GMP metabolic process
Cellular component: cell junction; tight junction; cell-cell junction; cytoplasm; membrane; bicellular tight junction; nucleus; plasma membrane
Genetic constraint (gnomAD): Loss-of-function variants: 38 observed, 105.44 expected, observed/expected ratio (o/e) 0.36, 90% interval 0.28 to 0.47. The upper end of that interval is the gene's LOEUF score, 0.47, which puts it in group 2 of 6, group 1 being the genes least tolerant of losing a copy. Missense variants: 1,478 observed, 1,737.6 expected, observed/expected ratio (o/e) 0.85, 90% interval 0.81 to 0.89. Synonymous variants: 526 observed, 613.89 expected, observed/expected ratio (o/e) 0.86, 90% interval 0.8 to 0.92.
Homologues: Orthologues: macaque MAGI3 (98% identical), pig MAGI3 (90% identical), rabbit MAGI3 (86% identical), rat Magi3 (86% identical), chimpanzee MAGI3 (83% identical), guinea pig MAGI3 (82% identical), mouse Magi3 (72% identical), tropical clawed frog magi3 (67% identical), zebrafish magi3a (55% identical), zebrafish magi3b (47% identical). Paralogues in human: MAGI2 (42% identical), MAGI1 (38% identical), GRIP1 (14% identical), GRIP2 (13% identical), SAV1 (7% identical), MAGIX (7% identical).
Diseases named in the same sentence as MAGI3 in open-access papers:
MAGI3 is named in the same sentence as 38 diseases in open-access papers, as found by Europe PMC text mining. Sharing a sentence is not in itself a finding about the gene and the disease. The quoted sentences say what the papers report.
breast carcinoma (9 papers, 2015 to 2021). "For example, in the MDA-MB-231 human breast cancer cell line and in primary human breast tumors, we found that oncogenic truncations of MAGI3 (MAGI3pPA) are caused by premature polyadenylation (pPA) triggered by intronic PAS activation." (PMID 29362392, 2018). "In this study, we have identified a breast cancer-associated pPA event at a cryptic intronic PAS in MAGI3, resulting in the production of a truncated, oncogenic gene product." (PMID 27205883, 2016). "Transformation caused by an independent MAGI3 truncation, also found in breast cancer, provides additional functional evidence for the cancer relevance of MAGI3 truncations." (PMID 27205883, 2016). "Collectively, these data demonstrate that the recurrent MAGI3pPA product and other breast cancer-associated MAGI3 truncations suppress the inhibitory interaction between full-length MAGI3 and YAP, thus providing a molecular link between their dominant-negative activity and their oncogenic nature." (PMID 27205883, 2016). "Importantly, we found that the C-terminal PDZ6 domain of MAGI3 is essential for MAGI3/YAP interaction, whereas the two independent breast cancer-associated MAGI3 truncations studied here – MAGI3pPA and MAGI3ΔC – lack this domain and fail to interact with YAP." (PMID 27205883, 2016). "The premature polyadenylation of MAGI1 and MAGI3 transcripts have been evidenced in human small intestinal neuroendocrine tumors and breast cancers, respectively." (PMID 34503076, 2021). "A role of MAGI3 in the control of YAP1-dependent transformation was recently evidenced in breast cancer, through the interaction of the C-terminus of the transcriptional regulator with the PDZ5 of the scaffolding molecule." (PMID 34503076, 2021). "SERPINB5, also known as the mammary tumor suppressor Maspin, was also identified as a likely MAGI3 interactor." (PMID 27205883, 2016). "Moreover, a recurrent MAGI3-Akt3 fusion protein that results in a truncated form of the MAGI3 gene fused in frame to AKT3 at the E17 residue of Akt3 has been identified in breast cancers." (PMID 27004402, 2016). "To determine whether pPA at the MAGI3 locus in human breast cancers might affect features of malignancy, we evaluated the role of MAGI3pPA on anchorage-independent growth." (PMID 27205883, 2016). "To corroborate these findings, we further asked whether other MAGI3 truncations found in breast cancer – generated by known alteration mechanisms – also exhibit oncogenic properties." (PMID 27205883, 2016). "Approximately 7.5% of breast cancer patients have the shortened version of MAGI3 due to premature polyadenylation, which indicates that this might be a more widespread mutation than previously thought." (PMID 27205883, 2016). "The occurrence of the MAGI3 pPA event in 7.5% (12 out of 160) of primary breast tumors and the absence of this event in matched tumor-adjacent normal tissues (0 out of 160) suggest that it is a tumor-specific and recurrent event that may play an important role in breast cancer pathogenesis." (PMID 27205883, 2016). "A MAGI3-AKT3 fusion gene, caused by a chromosomal rearrangement involving breakpoints at MAGI3 intron 9 and AKT3 intron 1, has been previously identified in breast cancer." (PMID 27205883, 2016). "This premature polyadenylation at a cryptic intronic poly(A) signal in MAGI3 identified in 7.5% of breast cancers -but not in tumor-adjacent control tissues- likely contributes to breast carcinogenesis." (PMID 34503076, 2021). "In breast cancer cells that upregulate MAGI3pPA, m6A levels in the large internal exon of MAGI3 are significantly reduced compared to cells that do not express MAGI3pPA." (PMID 29362392, 2018).
breast carcinoma (continued). "We also previously characterized MAGI3pPA and found that this truncation interfered with the ability of full-length MAGI3 to bind and inactivate YAP, thereby promoting malignant transformation in breast cancer cells by functioning in a dominant-negative manner." (PMID 29362392, 2018). "In addition, in breast cancer, upregulated m6A modification of HBXIP and MAGI3 results in tumour formation." (PMID 30031372, 2018). "In addition, a study revealed that high levels of m6A modification on MAGI3 lead to premature polyadenylation, switching its functional role from a tumour suppressor gene to a dominant-negative oncogene and ultimately promoting tumorigenesis of breast cancer." (PMID 30031372, 2018). "Since truncated MAGI3 induces YAP activation and anchorage-independent growth, whereas full-length MAGI3 suppresses YAP activity and the transformed phenotype, we hypothesized that the MAGI3 truncation products found in breast cancer possess dominant-negative activity." (PMID 27205883, 2016).
glioma (7 papers, 2015 to 2022). A benign or malignant brain and spinal cord tumor that arises from glial cells (astrocytes, oligodendrocytes, ependymal cells). "MAGI3 (PDZ domain-containing protein membrane-associated guanylate kinase inverted 3) was identified to be downregulated in glioma samples." (PMID 32149080, 2020). "In the present study, we identified a PDZ protein, membrane-associated guanylate kinase inverted 3 (MAGI3) as a novel inhibitor of Wnt/β-catenin signaling and showed that it suppressed the malignant phenotypes of glioma cells." (PMID 26452219, 2015). "Moreover, MAGI3 expression levels were found to be negatively associated with tumor grade and poor prognosis and activation of Wnt/β-catenin signaling in glioma datasets." (PMID 34198584, 2021). "Furthermore, analysis based on the Gene Expression Omnibus (GEO) glioma dataset showed association of MAGI3 expression with overall survival and tumor grade." (PMID 26452219, 2015). "This hypothesis is supported by the observations: MAGI3 overexpression downregulated the expression of c-Myc and Cyclin D1, which are target genes of β-catenin and appear to be associated with glioma progression." (PMID 26452219, 2015). "MAGI3 was also shown to negatively regulate the Wnt/β-catenin signaling suppressing the malignant phenotypes of glioma cells." (PMID 34198584, 2021). "We previously showed that MAGI3 inhibited malignant phenotypes of glioma through negatively regulating Wnt pathway by inhibiting β‐catenin transcriptional activity." (PMID 34510826, 2021). "In human gliomas, MAGI3 is downregulated at both mRNA and protein levels, and this expression is negatively associated with tumor grade and prognosis." (PMID 34503076, 2021). "In this context, MAGI3 knockdown in the PTEN defective U373 glioma cell line induces accumulation of the Wnt transcriptional targets cyclin D1 and Axin2 and enhances cell proliferation and migration." (PMID 34503076, 2021). "In gliomas, the expression levels of MAGI3 and PTEN were reported significantly down-regulated, and for glioma C6 cell line, overexpressed MAGI3 will inhibits Akt phosphorylation, and inhibits cell proliferation." (PMID 33324446, 2020). "Overexpression of MAGI3 inhibited proliferation, migration, and cell cycle progression of glioma cells and decreased subcutaneous tumor growth in mice by inactivation of Wnt/β-catenin signaling pathway." (PMID 32149080, 2020). "MAGI3 is underexpressed in high-grade gliomas compared to normal brain tissues, and MAGI3 overexpression inhibits the malignant transformation of glioma cells." (PMID 26452219, 2015). "Consistently, MAGI3 overexpression in glioma cells C6 suppressed expression of β-catenin target genes including Cyclin D1 and Axin2, whereas MAGI3 knockdown in glioma cells U373 and LN229 enhanced their expression." (PMID 26452219, 2015). "Here, we showed that the PDZ domain-containing protein membrane-associated guanylate kinase inverted 3 (MAGI3) was downregulated at the both mRNA and protein levels in human glioma samples." (PMID 26452219, 2015). "MAGI3 inhibited proliferation, migration, and cell cycle progression of glioma cells in its overexpression and knockdown studies." (PMID 26452219, 2015). "The results showed that the expression level of MAGI3 was higher in grade III (n = 26) than in grade IV gliomas (n = 59)." (PMID 26452219, 2015). "In conclusion, the present study identified MAGI3 as a novel tumor suppressor in glioma and showed its inhibitory effect on Wnt/β-catenin signaling." (PMID 26452219, 2015). "MAGI3 immunoreactivity was downregulated concomitant with upregulation of Cyclin D1 in glioma cells compared with adjacent normal cells." (PMID 26452219, 2015). "In the current study, we provide the first evidence that MAGI3 is underexpressed in glioma, and its expression level is negatively correlated with tumor grade and the prognosis of glioma patients." (PMID 26452219, 2015).
glioma (continued). "Taken together, these results identify MAGI3 as a novel tumor suppressor and provide insight into the pathogenesis of glioma." (PMID 26452219, 2015). "MAGI3 protein expression was significantly downregulated in glioma tissues compared with the normal controls (P < 0.01)." (PMID 26452219, 2015). "MAGI3 expression was markedly decreased in glioma tissues from 6 patients, with an approximately 85% reduction in expression levels compared to adjacent normal tissues." (PMID 26452219, 2015). "In glioma cells, MAGI3 overexpression inhibited proliferation and migration, whereas siRNA-mediated knockdown of MAGI3 enhanced cell proliferation." (PMID 26452219, 2015). "We previously reported the interaction between MAGI3 and β‐catenin in glioma cells." (PMID 34510826, 2021). "Since MAGI3 is widely distributed in many tissues, it may be involved in the pathogenesis of other tumors besides glioma." (PMID 26452219, 2015). "The inhibitory effect of MAGI3 on the malignant behaviors of glioma cells could be attributed to its capacity for suppressing β-catenin signaling in glioma." (PMID 26452219, 2015). "The results suggest that MAGI3 may inhibit the growth of C6 glioma xenografts in nude mice by blocking the Wnt/β-catenin pathway." (PMID 26452219, 2015). "The effect of MAGI3 on the migration of glioma cells was also assessed using a wound-healing assay." (PMID 26452219, 2015). "The mechanisms that contribute to MAGI3 downregulation in glioma remain to be elucidated." (PMID 26452219, 2015). "We further assessed the impact of MAGI3 on Wnt/β-catenin downstream target genes in glioma cells." (PMID 26452219, 2015). "In glioma cells, the mechanisms that contribute to MAGI3 downregulation remains unknown." (PMID 34198584, 2021). "The results indicate that MAGI3 might be a prognostic marker for glioma." (PMID 26452219, 2015). "Taken together, these data indicate that MAGI3 might attenuate glioma cell malignancy." (PMID 26452219, 2015). "Furthermore, MAGI3 overexpression in C6 glioma cell xenografts suppressed tumor growth in vivo." (PMID 26452219, 2015). "Overexpression of MAGI3 in the human U373 and LN229, and C6 rat glioma cell lines reduces cell proliferation, arrests the cell cycle, and inhibits migration." (PMID 34503076, 2021). "Of them, MAGI3 was the most downregulated gene, with 35% reduction of mRNA expression level in gliomas compared with the non-tumor tissues (P < 0.01)." (PMID 26452219, 2015). "In line with the results in glioma cells, MAGI3 did not affect β-catenin mRNA expression in xenograft tumors." (PMID 26452219, 2015). "Taken these results together, MAGI3 was richly expressed in glial cells, whereas only weak or no expression was detected in glioma cells." (PMID 26452219, 2015). "Finally, we demonstrated negative correlation between MAGI3 expression and activity of Wnt/β-catenin signaling through GSEA of three public glioma datasets and immunohistochemical staining of clinical glioma samples." (PMID 26452219, 2015).
colon cancer (6 papers, 2015 to 2023). "LPA2 receptor signaling regulates the function of colon cancer cells and is also associated with membrane-associated guanylate kinases, including MAGI-3 and NHERF-2." (PMID 32284748, 2020). "Another study reported that MAGI3, as a novel substrate-binding subunit of E3 ligase, can recognize cMYC and regulate its ubiquitination and degradation, thereby regulating colon cancer progression." (PMID 38105184, 2023). "The results of the present study may provide insight into the tumorigenesis of colon cancer, as MAGI3 downregulation could promote colorectal tumor growth by enhancing β-catenin signaling in colon cancer cells." (PMID 26452219, 2015). "NHERF-2 competes with MAGI-3 for binding to LPA2, which has the opposite effect on the function of the LPA2 receptor to regulate colon cancer cells." (PMID 32284748, 2020). "Indeed, MAGI3 is downregulated in colon adenocarcinoma tissues and suppresses the LPA-induced malignant phenotypes of colon cancer cells." (PMID 26452219, 2015). "Recently, Yun and his colleagues reported that MAGI3 by interaction with LPA2 and phospholipase C-β3, could decrease the tumorigenic capacity via inhibition of LPA-induced activation of NF-κB and JNK in colon cancer cells." (PMID 35864508, 2022).
colorectal cancer (3 papers, 2022 to 2024). A primary or metastatic malignant neoplasm that affects the colon or rectum. "On the contrary, MAGI3 overexpression reduced the expression of c-Myc and increased the level of c-Myc ubiquitination, confirming that MAGI3 is a major E3 ubiquitin ligase for c-Myc degradation in colorectal cancer cells." (PMID 38778217, 2024). "Overexpression of MAGI3 in colorectal cancer cells inhibits cell growth, promotes apoptosis, and enhances chemosensitivity to fluoropyrimidine-based chemotherapy." (PMID 36969025, 2023). "MAGI3 was a principal E3 ubiquitin ligase for c-Myc in colorectal cancer cells." (PMID 38778217, 2024). "In addition, MYC is marked for degradation by other ubiquitin ligases such as MAGI3 which is downregulated in poor prognosis colorectal cancer." (PMID 36969025, 2023).
Graves disease (3 papers, 2014 to 2022). Graves' disease is an autoimmune disorder that leads to overactivity of the thyroid gland (hyperthyroidism).It is caused by an abnormal immune system response that causes the thyroid gland to produce too much thyroid hormones. "Both were associated with an increased risk of Graves' disease (MAGI3- rs1230666: OR, 1.37 [95% CI, 1.22–1.54]; P = 1.2×10−7;BACH2- rs10944479: OR, 1.25 [1.12–1.39]; P = 6.2×10−5)." (PMID 24586183, 2014). "In addition, MAGI3 is also a risk gene for rheumatoid arthritis (RA), Graves′ disease, and other autoimmune diseases, indicating it can also cause JIA by affecting the human immune system." (PMID 36362342, 2022). "The associations of the MAGI3 locus with TPOAb-positivity and Graves' disease may therefore also be explained by linkage with disease-associated variants in PTPN22." (PMID 24586183, 2014). "The MAGI3 and BACH2 variants were associated with an increased risk of hyperthyroidism, which was replicated in an independent cohort of patients with Graves' disease (OR: 1.37, 95% CI 1.22–1.54, P = 1.2×10−7 and OR: 1.25, 95% CI 1.12–1.39, P = 6.2×10−5)." (PMID 24586183, 2014). "The current study provides insight into this phenomenon by showing that specific loci associated with TPOAbs and (subclinical) hypothyroidism, i.e. MAGI3 and BACH2, are also associated with Graves' hyperthyroidism in an independent case-control study." (PMID 24586183, 2014).
Crohn disease (2 papers, 2017 to 2021). A gastrointestinal disorder characterized by chronic inflammation involving all layers of the intestinal wall, noncaseating granulomas affecting the intestinal wall and regional lymph nodes, and transmural fibrosis. "Allelic associations between TJ-related genes (F11R, MAGI1, MAGI2, MAGI3, PARD3, PTEN, and TJP1) and IBD, Crohn’s disease (CD), or ulcerative colitis (UC) were investigated." (PMID 28545409, 2017). "Decreased expression of MAGI3 has also been described to contribute to the pathogenesis of IBD, and genetic variations of the gene MAGI2 have similarly been described in Crohn’s disease, ulcerative colitis, and celiac disease." (PMID 34198584, 2021).
breast tumors (1 paper, 2016). "In addition, MAGI3 was found to be part of a downregulated gene signature associated with breast tumor-initiating cells." (PMID 27205883, 2016). "We focused on data collected from primary breast tumors and matched normal tissues in order to establish whether pPA of MAGI3 is tumor-specific and recurrent." (PMID 27205883, 2016). "To determine whether the pPA product of MAGI3 is physiologically relevant in the context of primary human breast tumors, we analyzed whole transcriptome shotgun sequencing (RNA-Seq) data made available by The Cancer Genome Atlas (TCGA) and a previously published RNA-Seq study." (PMID 27205883, 2016).